GZMK (granzyme K)
Diseases named in the same sentence as GZMK in open-access papers (continued):
Sharing a sentence is not in itself a finding about the gene and the disease.
tumor (continued). "We identified several markers specifically expressed in the C0 cluster that was tumor-infiltrated, such as checkpoint inhibitor (LAG3), cytotoxicity-associated genes (GZMK), and oncogenic driver gene (FXYD2), further indicating that these CD8+ T cells were exhausted." (PMID 35812372, 2022). "Thus, we sought to elucidate the mechanistic details linking GZMK production by CD8+ TEM to tumor relapse." (PMID 36347862, 2022). "In comparing the occurrence and development of normal tissues and tumor tissues, we found that the expression levels of genes encoding activation and cytotoxic molecules, such as GZMB, GZMH, GZMK, GZMA, and NKG7, increased significantly and had strong correlations with signs of exhaustion." (PMID 35634956, 2022). "However, intratumor CD8+ TEM cells expressing higher levels of GZMK specifically and significantly accumulated only in HN T compared to their corresponding NAT, which supports the idea that the GZMK+ immune signature we found is tumor-specific." (PMID 36347862, 2022). "However, the GZMK+ resting NK cell subsets were first identified as potential tumor promoters." (PMID 39387546, 2024). "In addition, a report using surgical specimens successfully converted after lenvatinib treatment showed that the number of CD8-positive T cells (especially Granzyme K/CD8-positive T cells) was significantly higher in tumor samples after lenvatinib treatment than in the control." (PMID 37864726, 2024). "Considering the hard-to-reverse nature of exhaustion and the lack of mobility of TEX cells, these results further support the notion that TEX cells in tumor may be derived from GZMK+ TEM in ascites, in a process including cross-tissue migration and state transition." (PMID 37488416, 2023). "New clonotypes appearing in blood or tumor at disease progression were enriched for genes associated with cytotoxicity or stemness (FGFBP2, GNLY, GZMH, GZMK, IL7R, SELL and KLF2), and these might be harnessed for alternative cellular therapy or cytokine therapy." (PMID 36514045, 2022). "Moreover, several studies have reported that GZMK+CD8+ T cell defined as a pre-dysfunctional or transitional state could transform into an exhausted state under persistent tumor antigen stimulation." (PMID 35982235, 2022). "The change in the lymphocyte population was consistent with the elevated Granzyme K (GzmK) and decreased IL‐10 receptor mRNA transcript levels in the tumor, which may indicate either enhanced cytotoxic potential of lymphocytes or an overall increase in lymphocyte population in the TME." (PMID 33682324, 2021). "Cytotoxic/effector genes (GNLY, GZMA, GZMK, IFNG, NKG7, PRF1) were primarily expressed by T and NK cells, with notable upregulation in stRNA‐seq‐defined invasive front and tumor core regions." (PMID 41057994, 2025). "The identification of cytolytic enzyme expression levels (perforin, granzyme A, granzyme B, granzyme K, and IFN-γ) provided further insights into the anti-tumor functions of these T cells." (PMID 39979981, 2025). "Our analysis revealed significant correlations between GZMA, GZMB, GZMK and PRF1 expression and cytotoxic T cell infiltrates across various cancer types, underscoring the crucial roles of these genes in modulating the tumor microenvironment." (PMID 40002821, 2025). "Cytotoxic CD4+ phenotypes (i.e., GZMB+, GZMK+, Prolif which is largely cytotoxic, and MAIT) comprised the vast majority of CD4+ cells in blood that matched a TCR with tumor." (PMID 40299576, 2025). "In blood, before PD-1 blockade, tumor-TCR-matched CD4+ cells were predominantly GZMB+ in pre-atezolizumab blood (average 35%–37% of branches A and B), with a minority of GZMK+ (2.8%–5.2% of branches A and B)." (PMID 40299576, 2025). "In Module 4, correlations emerged among CD8 GZMK+ cells, CD4 Tm cells, tumor meta-programs related to the cell cycle, and classical and non-classical monocytes." (PMID 40890106, 2025).
tumor (continued). "Through spatial and molecular profiling, they found that CD8+ cytotoxic T cells in tumor-rich regions expressed effector molecules such as PRF1, GZMK, and TNF, indicating preserved cytotoxic function." (PMID 41001043, 2025). "Upon exposure to tumor cells, NK cells significantly decreased and slightly increased the expression of activated marker KIR2DL4 and the resting marker GZMK, respectively." (PMID 39387546, 2024). "These tumor-specific upregulated genes included inhibitory receptors, such as ENTPD-1 49 and PDCD1, as well as effector molecules, such as GZMK and IFNG, all involved in antitumor activity." (PMID 38948071, 2024). "Tumor-specific CD8 + T cells exhibited higher expression levels of cytotoxicity-related genes IFNG and GZMK, immune regulators FOS and JUN, and exhaustion markers TIGIT and PDCD1." (PMID 39033098, 2024). "Conversely, TCR+ Macrophages can directly eliminate tumor cells using cytotoxic granules, such as GZMA and GZMK." (PMID 38948071, 2024). "The CD56dimCD16hi subsets of NK cells within the tumor tissue showed lower expression levels of cytotoxic genes like PRF1, GZMB, GZMA, GZMH, and GZMK compared to normal tissues." (PMID 38552055, 2024). "Unlike other classic CD8+ T cells, which rely on the cytotoxic molecule Granzyme K (GZMK), CD8+ MAIT cells primarily exert their anti‐tumor effects through the non‐specific molecules, tumor necrosis factor (TNF)." (PMID 39716897, 2024). "Using FACS analysis, we observed that mice inoculated with CD74‐Over KLN205 cells exhibited a decrease in the relative proportions of CD4+ T cells, CD8+ T cells and GZMK+ Perforin+CD8+ T cells in the blood, spleen, tumour tissue and lymph nodes." (PMID 39113235, 2024). "Furthermore, it identifies that cathepsin B+ tumor‐associated macrophages may over‐activate CD8+ T cells in MIA, leading to an enrichment of granzyme K+ senescent CD8+ T cells, indicating the possibility of malignant progression behind the indolent appearance of MIA." (PMID 37991139, 2023). "in bladder cancer highlighted the presence of distinct subsets of CD4+ T CTL in the tumor microenvironment, expressing different combinations of cytolytic genes (GZMA, GZMB, GZMK, PRF1)." (PMID 37965314, 2023). "Consistently, the tumor-infiltrating GZMAhigh NK subcluster expressing a high level of cytotoxic genes (GZMA, GZMB, GZMK, GZMM, GZMH, PRF1, and GNLY) and FASL and TRAIL genes was most enriched in the PD-1+SMI group." (PMID 37430270, 2023). "Single-cell sequencing has recently been used to identify the tumor-suppressing functions of CD4 T cells, for example, the function of GZMK+CD4+ T cells in bladder cancer." (PMID 36357424, 2022). "Consistently, RNA seq analysis of MC38 tumor tissues showed AN3025 treatment elevated expression of immune activation genes such as ifn (gene for IFNγ) and gzmk (gene for Granzyme K)." (PMID 35251028, 2022). "Although the exhausted CD8+ T cells have been the majority of the tumor-infiltrating CD8+ T cells, CX3CR1-and granzyme K (GZMK)-expressing CD8+ T cells have also been identified." (PMID 34947886, 2021). "Eomes+ Tr1 cells, characterized by expression of GZMK and CHI3L2, have been detected in the tumor microenvironment." (PMID 34880348, 2021). "CD8+ T-cell tumor infiltration and tumoral gene expression of IFNG, CD8A, CXCL9, and granzyme K (GZMK) were also increased following MEDI0680 administration." (PMID 31439037, 2019). "Thus, it will be interesting to investigate further the neutrophil phenotype-dependent interaction with CD8+T cells and the generation of antitumor or tumor-supportive CD8+T cells, including GzmK+CD8+T cells." (PMID 41009359, 2025). "In order to infer fate trajectories of these different phenotypes that were clonally linked by a common TCR barcode, pseudotime analysis by Monocle was carried out specifically on cells with tumor-blood-matched TCRs from GZMB+, GZMK+, CXCL13+, Tregs, Prolif, and MAIT populations." (PMID 40299576, 2025).
tumor (continued). "The EOMES GRN, encompassing CD8A, GZMK, STAT5A, CXCR3, and LAG3, integrates cytotoxic effector functions, migratory capacity, and checkpoint regulation—features critical for sustained anti-tumor immunity." (PMID 40520886, 2025). "The fact that GZMK+ DN-Tem abundance was greater in patients than in healthy individuals and had tumor nonspecific bystander (viral-specific) clones raised an intriguing question as to its generation mechanisms." (PMID 40307573, 2025). "Furthermore, the presence of CD8+ memory T cells, particularly GZMK+ CD8 + Tem cells, in the tumour microenvironment underscores the potential for harnessing the immune system to combat HB." (PMID 40099956, 2025). "Among these, GZMK+ CD8+ T cells, GZMB+ CD8+ T cells, and NK cells exhibited high levels of effector cytotoxic genes such as GZMA, GZMB, NKG7, PRF1, and GNLY, contributing significantly to anti-tumor immunity." (PMID 40149859, 2025). "Quantitation using TCR network analysis further corroborated that cytotoxic CD4+ (GZMB+ and GZMK+) T cells were significantly overrepresented in clusters of tumor-blood matched TCRs over nonmatched TCRs in blood and tumor." (PMID 40299576, 2025). "Specifically, granzyme A (GZMA), granzyme B (GZMB), granzyme K (GZMK) and perforin-1 (PRF1) do not only induce apoptosis and modulate immune response within the tumor microenvironment (TME), but also have other diverse roles, such as potentially regulating homeostasis post-infection." (PMID 40002821, 2025). "Overall, GZMB+ cells comprised the majority (~50%) of circulating CD4+ cells with tumor-matched TCRs, and GZMB+ and GZMK+ cells together represented more than 40% of intratumoral CD4+ cells with blood-matched TCRs despite these cells constituting the minority of total CD4+ cells." (PMID 40299576, 2025). "Interestingly, we found that tumor-cell enriched areas and intratumor stroma were enriched in GZMH+ CD8+ T cells, while lymphocytes aggregates showed an enrichment in precursor GZMK+ CD8+ T lymphocytes." (PMID 38561380, 2024). "Furthermore, tumor-infiltrated CD8+ T and CD4+ T cells in the allografts highly expressed the activation/exhaustion markers, such as GZMB, GZMK, PDCD1, LAG3, HAVCR2, and CTLA-4." (PMID 37980406, 2023). "The abundance of CXCL13+ CD4+ T cells, the tumor antigen‐specific T cells to immune‐checkpoint blockade, was significantly higher in primary tumors, and a subset of CD4+ T cells had high expression levels of several cytotoxic genes, including GZMB and GZMK." (PMID 37743226, 2023). "Thus, we further checked TCR sharing between GZMK+ TEM and TEX/ANXA2+ TEM across different tissues and found that TEX and ANXA2+ TEM cells in tumor sites shared more TCR clones with ascites-derived GZMK+ TEM cells than tumor-derived GZMK+ TEM cells." (PMID 37488416, 2023). "Given that GZMK+ TEM cells were mostly enriched in ascites, their transitions to tumor-enriched clusters (TEX and ANXA2+ TEM) might happen together with cross-tissue migration." (PMID 37488416, 2023). "Overall, these studies confirm the existence of a direct, contact-mediated cross-talk between neutrophils and CD8+ T cells resulting into increased GZMK production, and support a model where GZMKhigh CD8+ T cells might foster tumor progression." (PMID 36347862, 2022). "Upregulated within the tumor-infiltrating CD4+ T cells were heat shock proteins (HSPA1A and HSPA1B), Jun and FOS constituents (FOS, JUN, and JUNB), MHC-II molecules (HLA-DRB), and secreted molecules (CCL5, GZMA, and GZMK)." (PMID 33504936, 2021). "As for T cell related cytotoxins, essential in tumor killing, stacked FPKM of 8 genes (PRF1, GZMM, GZMK, GZMH, GZMB, GZMA, FASLG, and FAS) demonstrated that these genes were more highly expressed 1.7-fold (P = 0.037) in IFNγ positive tumors compared to IFNγ negative tumors." (PMID 32265897, 2020).
tumor (continued). "In fact, when compared with the 75,302 known virus-specific CDR3 sequences in VDJdb40, a fraction of GZMK+.DN-Tem (particularly GZMK+.C3.DN-Tem-CO) contained clonotypes restricted to known viral epitopes, suggesting that not all GZMK+.DN-Tem are tumor specific." (PMID 40307573, 2025). "These cytotoxic cells express Eomes and GzmK together with uniquely high expression of the signaling lymphocytic activation molecule family member 7 (SLAMF7), a surface protein that was already described to characterize CD4+ T cells with cytotoxic potential in tumor and autoimmune diseases." (PMID 37965314, 2023). "In addition, we noticed that the expression of LAG3 and GZMK is higher than that of immune inhibitors, such as PD-L1, TIM3, and CTLA4, in the CD8+ T_3 cluster; thus, LAG3 or GZMK may be a better target for tumor immunotherapy in ccRCC." (PMID 35812372, 2022). "Finally, 8 genes related to anti-tumor immunity were obtained, which were APOL3, CCL5, CD8A, CD8B, CXCL9, GZMA, GZMK and PRF1.We found that the m6A regulatory factors YTHDC1, YTHDC2, and WTAP were positively correlated with m6A, while IGF2BP3 was negatively correlated." (PMID 34737950, 2021). "Additionally, it would be interesting to investigate the potential interactions between GZMK, TREM2, and OR4D10 and other immune-related genes in the tumor microenvironment, which could provide new insights into the complex interplay between cancer cells and the immune system." (PMID 40332815, 2025). "Notably, the CD8_Tem-GZMK subset was relatively closer to the CD8_Tex-LAYN subset compared to the CD8_Tn-LEF1 and CD8_Trm-KLRB1 subsets, aligning with recent studies that highlight the transition from effector memory T cells to exhausted T cells during tumor progression." (PMID 38596689, 2024). "Within tumor, blood-matched TCR phenotypes were predominantly not proliferating, but were instead consistently cytotoxic (GZMB+ and GZMK+ for CD4+, also GZMK+ and MAIT for CD8+), and also included noncytotoxic CXCL13+ CD4+ and Tregs as observed above." (PMID 40299576, 2025). "In contrast, non-responding tumours were more memory-like (FOS) and, upregulated GZMK, a typical CD8 TEM marker." (PMID 38030622, 2023). "Cytotoxic CD4+ circulate between the blood and tumor of bladder cancer patients, where they exist as clonally related but distinct pools of granzyme B+ effector cells dually inhibited by PD-1 and KLRG1, and effector memory granzyme K+ cells that are not mobilized by PD-1 blockade." (PMID 40299576, 2025).
cancer (44 papers, 2018 to 2026). A tumor composed of atypical neoplastic, often pleomorphic cells that invade other tissues. "The FAM46 gene is implicated in regulating T and B cells and found negatively associated with naïve CD4 + cells in pan-cancer GZMK encodes Ganzyme K, a serine protease closely associated with proinflammatory responses and impediment of wound-healing by inflammation and impaired epithelialization." (PMID 36267464, 2022). "Initially, we thought that cancer-associated chronic inflammation, which is common in malignant diseases, could be a key factor in accelerating the DP-to-DN transition and promoting the generation of GZMK+ DN-Tem." (PMID 40307573, 2025). "The analysis of copy number variation (CNV) mutations in GZMA, GZMB, GZMK and PRF1 across the various cancer types revealed significant associations with survival outcomes, highlighting their potential prognostic value." (PMID 40002821, 2025). "To assess the usefulness of GZMK, TREM2, and OR4D10 expression in predicting the prognosis of cancer patients, we examined the relationship between GZMK, TREM2, and OR4D10 expression and overall survival in the TCGA cohort." (PMID 40332815, 2025). "To further explore the impact of the SNV and CNV mutations in GZMA, GZMB, GZMK and PRF1 in the different cancers, we assessed the survival differences between mutant and wild-type forms of the genes." (PMID 40002821, 2025). "Genotype–tissue expression pan-cancer data and The Cancer Genome Atlas (TCGA) were used to investigate the expression of GZMK, TREM2, and OR4D10." (PMID 40332815, 2025). "This subtype was characterized by increased formation of TLSs, spatial cooption of PD-L1+ cancer cells, and enrichment of GZMK+ CD8+ T cells—features indicative of a more robust antitumor immune response." (PMID 40710213, 2025). "In subtype C, a larger number of infiltrated effector CD8 + T cells (CD8+/GZMK+) and spatial co-option with PD-L1+ cancer cells were observed compared to the other three subtypes." (PMID 39060379, 2024). "Immune-Activated subtype having the most idea long-term survival, had higher tertiary lymphoid structures, spatial co-option of PD-L1+ cancer cells, and GZMK+ CD8+ T cell." (PMID 39060379, 2024). "Immunohistochemistry analysis indicated significantly higher expression levels of GZMK in cancer tissues compared to normal tissues (P < 0.05)." (PMID 38833021, 2024). "It has also been found that GZMK plays an anti-cancer role in CM, activating immune signaling pathways and responses in low-risk patients, especially when CD8+ T cells are highly expressed, resulting in greater benefits from anti-PD-1 therapy." (PMID 38833021, 2024). "inferred two paths of T cell exhaustion via pan-cancer analysis: the first path (P1) through GZMK+ effector memory T (Tem) cells and the second path (P2) through ZNF683+CXCR6+ tissue-resident memory T (Trm) cells." (PMID 39393173, 2024). "A relative quantitative analysis of GZMK expression levels in these six pairs of tissues showed a mean expression level of 3.67 in cancer tissues compared to 1.33 in normal tissues, with a fold difference of 2.75 (P = 0.03, P < 0.05)." (PMID 38833021, 2024). "At the gene-level, the cytolytic granzyme A (GZMA) and K (GZMK) enzyme, CD8A and the chemokine CXCL10 illustrious of T and NK-cells and the testis antigen SPAG5 were associated with infiltration to cancer tissue." (PMID 37391505, 2023). "We first compared gene expression between recurrent and nonrecurrent cases, and we found that recurrence was associated with higher expression of cancer/testis antigen (CTA) genes including MAGEA12, GAGE1, and GAGE2C as well as with lower expression of GZMK." (PMID 37402831, 2023). "Interestingly, recent studies using scRNA-seq in CD8+ T cells isolated from patients with cancer have described cells expressing CXCR3 together with GZMK and EOMES as a predysfunctional cell population." (PMID 39485042, 2024).